DPP4 (dipeptidyl peptidase 4)
Diseases named in the same sentence as DPP4 in open-access papers (continued):
Sharing a sentence is not in itself a finding about the gene and the disease.
ovarian carcinoma (continued). "In human ovarian cancer, the existence of DPP4-mediated CXCL10 cleavage products was demonstrated, suggesting a relevant role for these mechanisms also in patients." (PMID 31482487, 2019). "Conversely, PARPi resistance in HRP ovarian cancer can be overcome by DPP4 inhibition." (PMID 40579444, 2025). "The presence of DPP4-cleaved shortened CXCL10 in human high-grade ovarian cancer tissues suggests that the truncated form of CXCL10 may induce an immunosuppressive tumor microenvironment." (PMID 37218983, 2023). "Sitagliptin treatment reduced melanoma growth in mice as a result of delayed chemokine processing, prolonged survival, and increased CD8+ T cell trafficking in a syngeneic ovarian cancer mouse model, highlighting the importance of DPP4 in the regulation of the immune landscape." (PMID 35158891, 2022). "Dysregulation of the type II transmembrane glycoprotein dipeptidyl peptidase 4 (DPP4) has been implicated in several cancer types including urothelial carcinoma, papillary thyroid carcinoma, metastatic prostate cancer and epithelial ovarian cancer." (PMID 33513866, 2021). "DPP4 attenuates C-X-C motif ligand 10 (CXCL10) and atypical chemokine receptor 2 (ACKR2) activity by regulating N-terminal processing, while DPP4 inhibitors may serve as second-line treatment for epithelial ovarian cancer." (PMID 34359286, 2021). "Similarly, whilst DPP4 expression in ovarian cancer cells varies according to cell type, studies disagree regarding in which cell types, and to what degree, DPP4 is expressed." (PMID 33143089, 2020). "Altered DPP4 function is also postulated as an underlying mechanism in the poor response of some high grade ovarian cancers, and the in vitro and in vivo interactions between DPP4 and specific cytokines are established as an important mechanistic contribution in different cancer types." (PMID 33143089, 2020). "Based on recent data suggesting that MMPs may mediate shedding of DPP4 from smooth muscle cells, we hypothesized that MMPs may play a similar role in ovarian cancer cells." (PMID 33143089, 2020). "Whether DPP4 shedding in ovarian cancer cells is directly mediated by MMP activity, via MMP-dependent activation of pro-enzymes, or by a more complex interrelationship with other protease systems requires further investigation." (PMID 33143089, 2020). "The functional role and prognostic significance of DPP4 expression in ovarian cancer thus remains unclear." (PMID 33143089, 2020). "High DPP4 expression in ovarian cancer cells is correlated with an epithelial phenotype and reduced invasiveness; conversely, DPP4 expression has also been associated with the enhanced migratory capacity and tumorigenic potential of ascites-derived cancer cells." (PMID 33143089, 2020). "Finally, a linear correlation of dipeptidyl peptidase 4 (DPP4) and CXCL10 expression was observed in ovarian cancer patients, suggesting a regulatory association between chemokine substrate and the protease DPP4." (PMID 31482487, 2019). "However, despite its positive prognostic value, DPP4 should be tested as a predictive marker for PARPi resistance, and its inhibition could also further improve PARPi therapy in BRCA-mutated ovarian cancer patients." (PMID 40579444, 2025). "Furthermore, DPP4-typical cleavage products of CXCL10 were detected in human ovarian carcinoma." (PMID 40579444, 2025). "Our data demonstrates a highly regulated relationship between DPP4 function and expression and hypoxia-induced proteases in the tumour microenvironment and suggests further studies are needed to elucidate the complex role of DPP4 in epithelial ovarian cancers and other solid tumours." (PMID 33143089, 2020). "In support of this, we show that chemokine-degrading proteases such as DPP4 confer resistance to PARP inhibition and are attractive targets for enhancing PARPi action even in HRP ovarian carcinomas." (PMID 40579444, 2025).
ovarian carcinoma (continued). "CD26/DPP4 expression was identified in numerous tumors, such as MPM, RCC, GIST, HCC, and colorectal, lung, prostate, and ovarian cancer." (PMID 34055551, 2021). "While using the DPP4 inhibitor sitagliptin had no additional benefit to olaparib in the Brca2-mutated model, it significantly impacted survival in the HRP ovarian cancer model." (PMID 40579444, 2025). "Likewise, it has been reported that hypoxia regulates DPP4 MMP-mediated proteolytic inactivation and shedding from ovarian cancer cells." (PMID 36230486, 2022). "Neither the expression nor function of DPP4 in ovarian cancer cells have previously been examined under conditions of hypoxic growth that mimic the tumour microenvironment." (PMID 33143089, 2020). "The discovery of a link between hypoxia, DPP4 expression and MMP-dependent shedding offers a much-needed new mechanistic understanding into potentially contradictory findings in the literature on DPP4 expression and its prognostic utility in ovarian cancer." (PMID 33143089, 2020). "However, the role of DPP4 and its potential as a therapeutic target in ovarian cancer has not been established." (PMID 33513866, 2021). "However, the role of hypoxia on DPP4 expression in ovarian cancer has never been evaluated." (PMID 33143089, 2020). "However, the influence of DPP-4 inhibitors was not investigated yet in ovarian cancer cells." (PMID 33256016, 2020).
Alzheimer disease (22 papers, 2020 to 2026). A progressive, neurodegenerative disease characterized by loss of function and death of nerve cells in several areas of the brain leading to loss of cognitive function such as memory and language. "With patients defined as having normal cognition, metformin was associated with better test performance over time, whereas DPP4 inhibitors were associated with lower cognitive decline in patients with Alzheimer’s Disease." (PMID 38152822, 2023). "DPP-4 inhibitors: In vitro studies have indicated that DPP-4 inhibitors possess neuroprotective properties in Alzheimer's disease models." (PMID 37809189, 2023). "This review aims to comprehensively assess the potential therapeutic applications of novel-generation antidiabetic drugs, including GLP-1 analogs, SGLT-2 inhibitors, and DPP-4 inhibitors, in the context of Alzheimer’s disease." (PMID 38002034, 2023). "Various DPP-4 inhibitors have shown promising effects in preclinical and clinical studies on several pathological processes of PD and Alzheimer’s disease (AD)." (PMID 36290663, 2022). "These intriguing findings suggest that DPP-4 inhibitors, typically used as antidiabetic medications, may hold promise as a therapeutic agent for Alzheimer’s disease." (PMID 38002034, 2023). "Saxagliptin is a dipeptidyl peptidase-4 (DPP-4) inhibitor and anti-diabetic and has potential to treat Alzheimer’s disease." (PMID 39459317, 2024). "demonstrate that the DPP4-i saxagliptin reduces beta-amyloid, tau accumulation (main culprits of neurodegeneration) and inflammatory markers and increases hippocampal GLP-1 and memory retention in mouse models of Alzheimer’s disease." (PMID 41480353, 2025). "Similarly, other DPP4-i including saxagliptin, vildagliptin, and sitagliptin were effective in increasing GLP-1 expression in the hippocampus of various animal models of Alzheimer’s disease, although these drugs are not efficient in crossing the BBB." (PMID 37508016, 2023).
renal failure (22 papers, 2011 to 2025). "Interim results (reported as of June 2021) showed that the risk of kidney failure was significantly reduced with empagliflozin treatment compared with DPP-4-inhibitor treatment." (PMID 37159343, 2023). "In contrast, as a new type of a dipeptidyl peptidase 4 (DPP-4) inhibitor, linagliptin tablets can be excreted through the intestine and can be used even in patients with renal insufficiency or on dialysis, with a good hypoglycemic effect." (PMID 36177313, 2022). "However, it should be noted that DPP-4 inhibitors should adjust the dosage based on eGFR level in order to ensure the safety of drug use in the population with renal insufficiency." (PMID 32368255, 2020). "Except saxagliptin, the safety of all DPP-4 inhibitors has been proven in patients with any level of eGFR; therefore, DPP-4 inhibitors may be more suitable than insulin for patients with severe renal insufficiency." (PMID 36142794, 2022).
depression (21 papers, 2018 to 2025). "Accordingly, in mice fed an obesogenic diet, increases in DPP4 activity in systemic circulation have been associated with a depression-like behavior, an effect that is counteracted by sitagliptin." (PMID 38961511, 2024). "Therefore, this study finds that there is less risk of depression associated with the use of DPP‐4 inhibitors for the treatment of T2DM." (PMID 31768258, 2019). "Among other common antidiabetic medications, DPP-4 inhibitors were found with weak signals of anxiety and depression." (PMID 39901452, 2025). "In conclusion, the intestinal microbiota can affect the development of depression through the metabolites equol, genistein and quercetin, which act on the critical targets of DPP4, CYP3A4, EP300, MGAM and NR1H4." (PMID 37433869, 2023). "This study investigated the risk of new onset depression between SGLT2I and dipeptidyl peptidase 4 inhibitor (DPP4I) users." (PMID 37000300, 2023). "Altered concentration or activity of DPP4 in the blood was observed in patients with autism spectrum disorders, anxiety, depression, and eating disorders, suggesting DPP4 dysfunction is involved in various psychiatric disorders." (PMID 34947986, 2021). "It was suggested that the use of DPP‐4 inhibitors and SGLT‐2 inhibitors decreases the risk of depression." (PMID 31768258, 2019). "Clinical studies have also confirmed the hypothesis that low plasma DPP4 activity is a characteristic marker of major depression and that changes in DPP4 enzyme activity play a role in the pathophysiology of major depression." (PMID 37433869, 2023). "Given the close relationship between diabetes and depression, there has been growing interest to study the modulatory effects of anti-diabetic medications on depression, including novel agents such as dipeptidyl peptidase 4 inhibitor (DPP4I) and sodium-glucose co-transporter 2 inhibitor (SGLT2I)." (PMID 37000300, 2023). "However, these authors observed a positive association of DPP4 and depressiveness alongside an inverse correlation of NPY with increased DPP4 activity indicating their possible interaction in the pathogenesis of depression." (PMID 33192409, 2020). "In the PPI network, DPP4, CYP3A4, EP300 MGAM and NR1H4 showed higher degrees and were identified as essential genes of intestinal microbiota influencing the occurrence of depression through the brain–gut axis." (PMID 37433869, 2023). "Thus, the use of DPP‐4 inhibitors are more suitable than nonuse in terms of the risk of depression." (PMID 31768258, 2019). "In humans, incretin-based therapies, which include DPP-4 inhibitors and GLP-1 analogs, reduce depression symptoms in patients who have type 2 diabetes." (PMID 30186247, 2018). "Obese patients may have higher DPP-4 levels from adipose tissue, and DPP-4 might induce depression by activating the immune system and promoting proinflammatory cytokine secretion." (PMID 35281896, 2022). "Although the effects of metformin, DPP-4 inhibitors, and SGLT-2 inhibitors on migraine have not been specifically reported, the use of these medications has been associated with a lower risk of depression, a common comorbidity of migraine." (PMID 39333866, 2024). "However, a recent study reported that low doses of metformin, DPP4 inhibitors, GLP1 analogs, and especially SGLT2 inhibitors were associated with lower odds of depression than non-users of these medications." (PMID 36734114, 2023).
liver disease (21 papers, 2010 to 2025). "Elevated circulating DPP-4 levels are associated with more severe liver disease, particularly in individuals with MASLD." (PMID 40244398, 2025). "DPP4 has been largely investigated in many hepatic diseases, and initial evidence is available on the association between DPP4 and NAFLD." (PMID 36140405, 2022). "Our study participants had overall mild liver disease; thus, the existence of association between hepatic DPP4 and histological signs of liver damage in individuals with more advanced liver impairment, cannot be definitively ruled out." (PMID 32852705, 2021). "Elevated concentrations of plasma DPP4 are associated with liver disease severity and fibrosis." (PMID 36472923, 2023). "Some studies reported altered DPP4 levels in a number of hepatic diseases, such as chronic C hepatitis, hepatocarcinoma and cirrhosis; however, data in literature on circulating DPP4 activity and its concentration in NAFLD/NASH are contrasting." (PMID 32852705, 2021). "This association between liver disease and DPP-4 has been confirmed in other studies, showing higher plasma levels as well as higher hepatic Dpp4 expression in the patients compared to healthy individuals." (PMID 30828317, 2019). "This upregulation of hepatic DPP4 expression is thought to be responsible for elevated DPP4 serum level in patients with liver disease." (PMID 26284071, 2015). "The correlation among γGT, ALT and serum DPP-4 activity and also between serum DPP-4 activity and HOMA2-IR in NAFLD strongly suggests that serum DPP-4 activity should be considered as a novel liver disease biomarker." (PMID 20805868, 2010). "Hepatic DPP4 has been shown to be increased in severe liver diseases and cancer." (PMID 32852705, 2021). "Also, the liver is an organ with high DPP4 expression, which is influenced by hypoxia, and DPP4 levels are increased in inflammatory liver diseases." (PMID 31835410, 2019). "Also, markers of liver function were not evaluated, since liver diseases have already been associated with altered DPP4 levels and activity." (PMID 36197412, 2022). "Thus, the authors claim that enhanced DPP4 expression in NAFLD liver may rather be associated with IR than triglyceride accumulation and may promote the progression of liver disease via subsequent deteriorations in glucose metabolism." (PMID 26284071, 2015). "Increased expressions of DPP-4 in serum and the liver have been reported in patients with HCV-related liver disease, and a higher concentration of truncated CXCL10 has been associated with failure to spontaneously clear acute HCV infection." (PMID 34604157, 2021). "Remarkably, in this unbiased analysis, four clinical markers used in liver disease—ALT, AST, ALP, and GGT—clustered into a single group together with a panel of five proteins of special interest—PIGR, DPP4, ANPEP, TGFBI, and APOE." (PMID 30824564, 2019). "The other four are also highly relevant for liver disease: APOE (apolipoprotein E), dipeptidyl peptidase‐4 (DPP4), TGFBI (transforming growth factor‐beta‐induced protein ig‐h3), and aminopeptidase N (ANPEP)." (PMID 30824564, 2019). "Inhibition of dipeptidyl peptidase 4 (DPP4), a regulator of glucose metabolism, showed protective effects in several inflammatory conditions, including cardiovascular diseases, renal disorders, liver diseases, multiple sclerosis, and IBDs." (PMID 39359253, 2024). "Surprisingly serum DPP-4 activity was not increased in the T2D group provided that patients with clinically obvious liver disease were intentionally excluded from this study group." (PMID 20805868, 2010). "The fasting serum DPP-4 activity was not increased in T2D provided that patients with liver disease were intentionally excluded." (PMID 20805868, 2010).
liver disease (continued). "Dipeptidyl peptidase-4 has been demonstrated to define fibroblast populations within human skin biopsies, and DPP4+ fibroblasts have been shown to express higher levels of myofibroblast markers and collagen, but whether these pathways are relevant in liver disease remains to be determined." (PMID 32231442, 2020). "In humans, plasma DPP-4 activity is higher in patients with non-alcoholic fatty liver disease irrespective of their glucose tolerance, whereas it was not elevated in patients with T2DM in whom liver disease had been excluded." (PMID 30828317, 2019).
malignant mesothelioma (21 papers, 2009 to 2025). A malignant neoplasm of the pleura or peritoneum, arising from mesothelial cells. "Moreover, in preclinical model systems of RCC and malignant mesothelioma, the presence of blocking anti-CD26/DPP4 antibodies inhibited tumor growth and metastasis." (PMID 34885056, 2021). "Meanwhile, the humanized anti-CD26/DPP4 mAb YS110 (NCT03177668) has already been tested in humans for its safety and efficacy for the treatment of aggressive malignant mesothelioma, a disease with otherwise still very limited treatment options." (PMID 34885056, 2021).
non-alcoholic fatty liver disease (21 papers, 2010 to 2025). "In this sense, not only Dpp-4 hepatic mRNA expression has been reported to be upregulated in patients with non-alcoholic fatty liver disease, but also associated with steatohepatitis." (PMID 37371501, 2023). "An elevated DPP-4 mRNA expression in the livers of patients suffering from non-alcoholic fatty liver disease (NAFLD) is observed." (PMID 37287751, 2023). "Recent studies show that DPP4 expression is elevated in the liver of patients with nonalcoholic fatty liver disease (NAFLD)." (PMID 36232933, 2022). "DPP4 is also a hepatokine, and levels of this enzyme have thus been seen to be elevated in chronic liver diseases including hepatitis C, hepatitis B, non-alcoholic fatty liver disease (NAFLD) and hepatocellular carcinoma." (PMID 33691757, 2021). "In addition, circulating DPP-4 levels have been shown to increase in patients with non-alcoholic fatty liver disease, and are positively correlated with liver enzymes." (PMID 38476668, 2024). "DPP4 and AHSG were both suggested as biomarkers for non-alcoholic fatty liver disease." (PMID 30188931, 2018).
Glucose intolerance (20 papers, 2011 to 2026). Glucose intolerance (GI) can be defined as dysglycemia that comprises both prediabetes and diabetes. "Recently, the circulating levels of endogenous soluble DPP4 were found to be dissociated from the extent of systemic inflammation, glucose intolerance and white adipose tissue inflammation; therefore, the search for DPP4 inhibitors is a viable approach." (PMID 35630534, 2022). "Previous reports showed that a GLP-1 receptor agonist prevented GC-induced glucose intolerance, but that a DPP-4 inhibitor failed to improve this effect." (PMID 30285859, 2018). "HFD mice showed weight gain and administration of linagliptin (a DPP-4 inhibitor) did not result in a leaner phenotype, although glucose intolerance was improved." (PMID 28771625, 2017). "Linagliptin administration almost completely suppressed the circulating DPP-4 activity in db/db mice, but did not significantly reduce blood glucose or ameliorate glucose intolerance in db/db mice." (PMID 25986579, 2015). "In other words, DPP-4 may exert a vascular toxicity directly without the mediation of glucose intolerance." (PMID 38256615, 2024).